MTOR (mechanistic target of rapamycin kinase)
Diseases named in the same sentence as MTOR in open-access papers (continued):
Sharing a sentence is not in itself a finding about the gene and the disease.
tumor (continued). "The findings from current study demonstrate that PGAM1 plays critical roles in mTOR-mediated Warburg effect and tumor growth." (PMID 29362480, 2018). "Liver Kinase B1 (LKB1)/AMPK/mTOR signaling is thought to be the fundamental mechanism behind the suppression of tumor cells proliferation." (PMID 29958416, 2018). "Tumor cells showed high levels of AKT/mTOR and Ras/MAPK cascades as well as elevated glycolysis and lipogenesis, which are often induced in human HCC samples." (PMID 29303510, 2018). "Currently, inhibition of mTOR activity by rapalogs is the only available therapeutic strategy to control tumor growth in these patients." (PMID 30266942, 2018). "Future studies of agents targeting the MAPK and PI3K/mTOR pathway should include alternative dosing schedules and further explore the relationship between tumour type, genomic alterations, and efficacy." (PMID 30425349, 2018). "We previously reported that inhibition of mTOR (mammalian target of rapamycin) with rapamycin decreased splenomegaly and tumor development in LMP2A/MYC tumors." (PMID 30135222, 2018). "Diminished intracellular glutamine uptake suppresses the expression of TCA cycle intermediates, blocks mTOR signaling and tumor cell proliferation, and promotes autophagy and cell death." (PMID 29562706, 2018). "mTOR is documented to regulate fundamental cell processes such as embryonic development, homeostasis, tumor growth and metabolism." (PMID 29719593, 2018). "In good accordance with our data, HDAC inhibition suppressed epithelial–mesenchymal plasticity and stemness activity observed in mesenchymal-like tumor cells resistant to Akt-mTOR pathway inhibitors." (PMID 30200497, 2018). "The aberrant regulation of the PI3K/Akt/mTOR axis often confers a proliferative advantage to tumor cells and contributes to the development of drug-resistance mechanisms." (PMID 30139984, 2018). "This all suggests that PI3K/mTOR pathway inhibitors are more efficient in tumours with activated PI3K signalling." (PMID 30104481, 2018). "Consistent with the findings in cultured cell lines, TSPf also downregulated RNF6 expression along with inactivated AKT/mTOR signaling in tumor tissues." (PMID 29997504, 2018). "It is caused by mutations in TSC1 or TSC2 genes, which result in overactivation of the mammalian target of rapamycin (mTOR) pathway and subsequent tumor growth in multiple organs." (PMID 29701176, 2018). "mTOR (mammalian target of rapamycin), whose hyper-activation is characteristic for many tumours, promotes metabolic alterations, macromolecule biosynthesis, cellular growth and survival." (PMID 30574020, 2018). "These tumors are characteristically driven by deleterious mutations in the tumor suppressors TSC1 and TSC2, whose gene products typically act to inhibit mTOR." (PMID 30285856, 2018). "Programmed death-1 can be found expressed also on tumor cells, and PD-1 triggering on melanoma cells increases three-dimensional growth capability with concomitant activation of the mTOR pathway." (PMID 30108594, 2018). "Licensed treatment options targeting this pathway currently exist such as mTOR inhibitors, everolimus and temsirolimus, which have both been used in renal cell carcinoma among other tumours." (PMID 29662627, 2018). "Simultaneous targeting of PI3K, AKT and mTOR is required for effective tumor suppression by promoting sustained AKT, S6K1 and 4E-BP1 dephosphorylation and induction of apoptosis." (PMID 29357370, 2018). "Generally, the Jak/Stat signaling pathway, T cell receptor signaling pathway and PI3K/Akt/mTOR signaling pathway play important roles in moderation of anti-tumor immune defense." (PMID 30139984, 2018). "The activity of S6 was lower in climacostol-injected tumours (at day 16 of treatment) while phosphorylated AMPKα increased, thus confirming that climacostol inhibits and stimulates mTOR and AMPK pathways, respectively." (PMID 30584259, 2018).
tumor (continued). "The mTOR inhibitor, rapamycin, results in direct inhibition of IL-1α synthesis (and consequently IL-6 secretion) which successfully prevented the tumor-promoting effects of senescent fibroblasts." (PMID 29868482, 2018). "Our laboratory has previously shown that the mTOR signaling pathway, a master regulatory pathway controlling cellular metabolism and growth, is critical in the progression of both of these tumor models." (PMID 30513596, 2018). "In tumour bearing mice, mTOR activation is maintained, while the activation of protein synthesis is blocked." (PMID 29417752, 2018). "Free intracellular Ca2+ regulates the MAPK and PI3K/AKT/mTOR pathways as a second messenger, and thereby affects cell death and the cell cycle in tumor cells." (PMID 29514603, 2018). "The binding of tumor cells to bone marrow osteoblasts induces TANK binding kinase 1 (TBK1) expression that leads to inhibition of mTOR signaling and cell cycle arrest." (PMID 30180883, 2018). "The expression of mTOR, which is a key regulator in cell survival, was correlated with tumor stages in clinical-pathological study, whereas the suppression of mTOR and its downstream S6K reduced growth in OSCC cells." (PMID 29381751, 2018). "These drugs showed a better anti-tumor activity with respect to the first generation of mTOR inhibitors because they were able to inhibit PI3K and suppress the activation of both mTOR complexes." (PMID 29772672, 2018). "Since GOLPH3 activates mTOR signaling through the phosphorylation of specific substrates of mTORC1 and mTORC2, increasing the sensitivity of tumor cells to rapamycin in vivo." (PMID 29996891, 2018). "Wild type TSC1 and 2 combine to form a complex involved in tumor suppression that inactivates the GTPase Rheb, thus decreasing mTOR signaling which relieves mTOR-mediated inhibition of autophagy." (PMID 30443293, 2018). "PI3K/AKT/mTOR was reported to play key functions on tumor initiation and progression as well as angiogenesis." (PMID 29890617, 2018). "Here, we review the putative roles played by mTOR in cellular processes relevant to tumour cachexia and highlight the experimental evidence of mTOR signalling importance in these processes." (PMID 30061533, 2018). "In conclusion, the data suggest that PTS is an effective anti-tumor agent with in vitro and in vivo efficacies through inhibition of both Akt-dependent and -independent mTOR/p70S6K pathways." (PMID 30555320, 2018). "We have previously shown that the LMP2A-induced tumor development and splenomegaly are very sensitive to the Lyn inhibitor dasatinib and the mTOR inhibitor rapamycin." (PMID 30135222, 2018). "The phosphorylated tumor suppressor gene PTEN negatively regulates PI3K, whereas low expression of PTEN activates the PI3K/Akt/mTOR pathway leading to tumor formation." (PMID 30104473, 2018). "In particular, it is worth to note that while PD901 efficiently inhibited the Ras/MAPK pathway, the AKT/mTOR cascade remained elevated in K-Ras/NICD tumor tissues." (PMID 29348467, 2018). "Studies on preclinical models of panNETs (e.g., RIP1-Tag2 oncomice) showed that activating alterations of mTOR were specific of tumor cells, when compared to normal tissue, and that treatment with rapamycin reduced proliferation and increased apoptosis." (PMID 29509701, 2018). "Taken together these data suggest that inhibition of mTOR alone is sufficient to impair DNA repair and increase DNA damage, resulting in tumor regression and high percentage of complete response when combined to a PARP inhibitor." (PMID 30038706, 2018). "Treatment of some tumor entities with mTOR-Is, i.e. Kaposi sarcoma, has been shown highly efficacious." (PMID 29659588, 2018). "Further, in vitro studies showed that both PD-L1 antibodies and PD-L1 knockdown in tumor cells impaired sarcoma cell glycolysis and inhibited intracellular Akt/mTOR signaling, indicating the role of PD-L1 in modulating intracellular signaling pathway." (PMID 30687086, 2018).
tumor (continued). "These proteins interact with each other to form a tumour suppressor complex, which inhibits the mammalian target of rapamycin (mTOR) pathway." (PMID 30039053, 2018). "It has also been reported that mTOR is associated with EGFR resistance, blocking mTOR pathway can interfere with tumor growth." (PMID 29455664, 2018). "A significant association was seen between both positive expressions of cytoplasmic p-AKT and p-mTOR with a more aggressive tumour subtype (p<0.0001 and p = 0.0005, respectively, X2 test) and higher grade (p = 0.007 and p = 0.0103, respectively, X2 test)." (PMID 29902261, 2018). "The mutations of either TSC1 or TSC2 gene activate the mammalian target of rapamycin (mTOR) signaling pathway, resulting in cellular aberrant function and tumor growth." (PMID 30107845, 2018). ", oncotargets are gerotargets that are also mTOR activators, while tumor and aging suppressors are mTOR inhibitors." (PMID 30594910, 2018). "In support of the in vitro studies, in vivo xenograft studies revealed that duvelisib in combination with the mTOR inhibitor everolimus led to greater tumor growth inhibition compared to single agent administration." (PMID 30067771, 2018). "Greater tumor growth inhibition and pro-apoptotic activity have been observed than when employing single-target Akt/mTOR or HDAC inhibitors in vitro and in vivo." (PMID 30200497, 2018). "Research data further demonstrated that PI3K/mTOR double target inhibitors have a great potential in the process of anti-tumor therapy." (PMID 29954109, 2018). "EMT ensues when stressors act on tumor cells in the presence of nutrient sufficiency, and mechanistic target of rapamycin (mTOR) appears to be the crucial signaling node for EMT induction." (PMID 30013478, 2018). "It seems counterintuitive that mTOR inhibition allows tumor growth, but possibly under stress or nutrient-poor conditions autophagy initiation provide the required nutrients." (PMID 29662490, 2018). "The mTOR signaling pathway is frequently activated in tumor cells, resulting in the activation of its growth-promoting functions and the inhibition of autophagy." (PMID 30363988, 2018). "The most common mutation detected in primary tumor tissues was PIK3CA (6 patients, 37.5%), followed by ERBB2, mTOR and INPP4B (5 patients for each one, 31.25%)." (PMID 30167082, 2018). "In tumor cells, mutations or deletions in PTEN are common, and enable the increased activation of the PI3K/AKT/mTOR pathway; this leads to aberrant activation of this pathway." (PMID 29455668, 2018). "mTOR induce transcription of many genes involved in aerobic glycolysis and tumor growth, including HIF-1α, nuclear factor-κB, and c-Myc, among which HIF-1a was previously demonstrated to be inhibited by Sal-B treatment." (PMID 29789538, 2018). "In mammalian cells, TOR is named mammalian Target of Rapamycin (mTOR) that plays a central role in tumor growth, survival and drug resistance." (PMID 29755672, 2018). "The AMPK/mTOR axis is a well-documented cell signal pathway that is frequently used to elucidate the anti-tumor mechanism of metformin." (PMID 29416762, 2018). "HIF1a is an important transcription factor that helps the tumor cells acquire aggressive and drug-resistant phenotypes, and it is identified as a down-stream molecule of the mTOR signal pathway." (PMID 29416762, 2018). "Adenovirus-mediated expression of EVA1A in various tumor cell lines promoted autophagy via inhibition of mTOR and induced apoptosis via activation of caspase-3, inhibiting tumor cell growth." (PMID 29749374, 2018).
tumor (continued). "Taken together, the inhibited cell proliferation and induced cell apoptosis effect of AM extract via PI3K/AKT/mTOR pathway confirmed the anti-tumor potential of AM." (PMID 29523109, 2018). "Accumulating evidence has shown the role of the PI3K/Akt pathway in the mechanisms of EPS8 associated tumor proliferation, survival and drug resistance by activating downstream targets, such as FOXM1, mTOR, MMP-9 and caspase-9." (PMID 29357910, 2018). "A recent study showed that activation of the phosphoinositide 3-kinase/protein kinase B (PKB), also known as Akt/mammalian target of rapamycin (PI3K/Akt/mTOR) signaling pathway correlated with tumor progression and reduced patient survival." (PMID 29510727, 2018). "Rapamycin and its derivatives, such as everolimus, are selective mTOR inhibitors that have been shown to block mTOR modulation of cell cycle progression, angiogenesis and apoptosis in several tumor cell models." (PMID 29938004, 2018). "PI3K/Akt/mTOR signaling has been confirmed as a critical regulator during tumor progression, including cell–cell adhesion, proliferation, and migration." (PMID 29567987, 2018). "Phosphorylation of Erk1/2 increased in the subcutaneous tumor which can be one of the mechanism that results in active mTOR pathway." (PMID 29415661, 2018). "Hyperactivation of the major Pro‐survival signaling kinases Akt and mTOR is present in several types of tumors including RCC, and overexpression of HIF‐1α and HIF‐2α is linked to tumor progression of RCC." (PMID 30107094, 2018). "We further examined the effect of P.A treatment on EGFR, AMPK, mTOR, Akt, and death receptor cascades in protein extracts derived from tumor tissues." (PMID 29899551, 2018). "Activation of the PI3K/AKT/mTOR pathway is involved in tumor progression and reduced patient survival." (PMID 29716528, 2018). "Rapamycin and its analogs, sirolimus, everolimus and temsirolimus, inhibit mTOR pathway and are anti-tumor drugs used for metastatic renal cell carcinoma, pancreatic neuroendocrine tumors and advanced breast cancer." (PMID 29764404, 2018). "Expression of MET or MTOR was significantly higher in tumor tissues than in normal pleura in 66/92 (71.7%) and 46/95 (48.4%) MPM, respectively." (PMID 29755689, 2018). "Our in vivo results using NSG xenografts showed that combination of Vismodegib and BEZ235 or their combination individually with cisplatin significantly decreased MB tumor growth and increased survival of xenograft mice by targeting HH and mTOR pathways." (PMID 29682173, 2018). "The results showed that the expression level of mTOR is higher than that in the adjacent non-tumor liver tissue, and protein expression level of mTOR was positively correlated with malignancy and poor prognosis." (PMID 30526568, 2018). "NF-1 gene mutations can lead to dysregulation of RAS/MAP kinase and mammalian target of rapamycin (mTOR) signaling pathways which can lead to development of several types of neoplasms." (PMID 29849532, 2018). "In spite of mTOR crucial role in tumor progression, the first generation of mTOR inhibitors (rapamycin and rapalogs) have shown limited effects in phase I/II clinical trials in solid tumors." (PMID 29755672, 2018). "Since then many reports have appeared comparing Calcineurin- and mTOR-Inhibitors in every possible combination assessing not only the immunological potency but also looking closely at the tumor incidence." (PMID 29659588, 2018). "Because LAT1 and ASCT2 function cooperatively to regulate leucine transport and activate the mTOR pathway, these covalent inhibitors can be potentially efficacious drugs in suppressing tumor growth by exerting a dual inhibition." (PMID 29695141, 2018). "This supports the observation that mTOR signaling and inhibition induces differential responses on tumor cell repair compared to normal cell repair." (PMID 29518028, 2018).
tumor (continued). "The ORs for IGF1R and p-mTOR additionally adjusted for grade, tumor size and positive lymph node status were respectively 2.32 (95%CI:1.02–5.30; p = 0.05) and 2.58 (95%CI:0.97–6.81; p = 0.06)." (PMID 29486734, 2018). "GAS6 regulates part of the conversion of tumor cells into stem cells via its receptor Mer that activates the mTOR signaling pathway following cell to cell contact." (PMID 30180883, 2018). "The pivotal role of PI3K/Akt/mTOR signaling in proliferation and survival of tumor cells nominates this pathway as a target for therapeutic intervention." (PMID 29515122, 2018). "The mTOR inhibitor Everolimus inhibited downstream mTOR signaling and induced cytotoxicity in the metastatic tumor cells." (PMID 30176882, 2018). "The mTOR pathway is frequently reported to be involved in tumor survival and progression via two different functional protein complexes, mTORC1 and mTORC2." (PMID 29554968, 2018). "Deregulation of mTOR expression is very common in tumor cells and it is targeted in many NB studies, as its inhibition destabilizes MYCN, reduces NB growth, and induces excessive autophagy activation that will result in the stimulation of cell death." (PMID 29371588, 2018). "The fact that G-CSF is a downstream target of the mTOR pathway in tumor cells, suggests that it is a mediator of mTOR-driven MDSC accumulation." (PMID 30213113, 2018). "In this regard, we noted previously in MMTV-PPARd transgenic mice that PLAC1 RNA and protein were markedly upregulated at the onset and throughout tumor development, and were reduced following treatment with the mTOR inhibitor everolimus." (PMID 29432428, 2018). "Transporters have been reported to be amino acid sensors involved in controlling mTOR recruitment and activation, which is crucial for the growth of both normal and tumor cells." (PMID 30419950, 2018). "The Akt pathway is known to be involved in tumor metastasis, and a target of AKT, mTOR, is associated with promoting proliferation and differentiation, and inhibiting apoptosis." (PMID 30258464, 2018). "Accordingly, we introduced 4-amino quinazoline structure into PI3K/mTOR inhibitor to investigate antiproliferative activity of 4-amino quinazoline structure on tumor cells." (PMID 29954109, 2018). "Stretch activation of mTOR and protein synthesis is disrupted in by tumour derived media and interleukin‐6 (IL‐6) in cultured myotubes." (PMID 29417752, 2018). "Growing body of evidence shows that inhibition of mTOR protein kinase results in autophagy activation which in turn can be either beneficial or detrimental for tumor survival." (PMID 30250843, 2018). "As a downstream effector of mTOR, PGAM1 is critical for oncogenic mTOR-mediated cell proliferation and tumor formation." (PMID 29362480, 2018). "Enhanced cell growth and tumour progression as a result of LIF pathway activation has been linked to downstream activation of the JAK/STAT3 and Akt/mTOR pathways." (PMID 30263091, 2018). "Eventually, in order to address tumor cell heterogeneity, we have proposed a three-pronged therapeutic approach based on a cytotoxic drug, an mTOR inhibitor and an inducer of autophagic cell death." (PMID 30013478, 2018). "For which tumor entities, other than NMSCs mTOR-Is have a beneficial effect we cannot tell by this analysis." (PMID 29659588, 2018). "We evaluated the antitumor activity of the combination of MC‐4 and everolimus in RCC xenograft mouse models to investigate the relevance of coordinate autophagy and mTOR inhibition in RCC tumor growth in vivo." (PMID 30160042, 2018). "To better understand the mechanism by which ACY-1215 caused tumor cell cycle arrest and apoptosis, we demonstrated that ACY-1215 not only effectively inhibited phosphorylation ERK, but also inhibited PI3K/AKT/mTOR signaling pathways." (PMID 30050135, 2018).